CDC20 (cell division cycle 20)
Diseases named in the same sentence as CDC20 in open-access papers (continued):
Sharing a sentence is not in itself a finding about the gene and the disease.
oral cancer (4 papers, 2012 to 2020). "Mechanistically, overexpression of Cdc20 caused impairment of the spindle assembly checkpoint and aneuploidization in oral cancer." (PMID 28165402, 2017). "Overall expression status of Mad2, BubR1, Aurora B, and Cdc20 in oral cancer seems concordant between different reports, with a general tendency to upregulation, except for Mad2." (PMID 24995269, 2014). "In this review, we address the state of our knowledge regarding the SAC defects and the underlying molecular mechanisms in oral cancer, and discuss their therapeutic relevance, focusing our analysis on the core components of SAC and its target Cdc20." (PMID 24995269, 2014). "Consistently, Cdc20 overexpression in oral SCC histological samples has been linked to a poor prognosis, suggesting Cdc20 as a novel independent prognostic factor, as well as a molecular marker to categorize high-risk oral cancers subgroups." (PMID 32560247, 2020).
renal carcinoma (4 papers, 2019 to 2023). A carcinoma arising from the epithelium of the renal parenchyma or the renal pelvis. "Overexpression of CDC20 has been reported in various malignancies and high expression of CDC20 has been associated with high tumor grade in bladder, cervical, colon, endometrial, gastric, liver, ovarian, prostatic, and renal carcinomas." (PMID 30765611, 2019). "Overexpression of CDC20 and CDK1 has been reported in various malignancies, which are also associated with high tumor grade in cervical, colon, and renal carcinomas 32-34." (PMID 36605491, 2023). "Taken together, these studies support the notion that UBE2C and CDC20 are hub genes in different types of renal cancer." (PMID 36385010, 2022). "In order to diagnose and evaluate the prognosis of renal cancer, a nomogram was constructed to analyze the relationship between 8 clinicopathological characteristics (age, gender, race, grade, stage, T, M, and N) and CDC20 gene expression." (PMID 35800227, 2022). "However, modest levels of CDC20 protein expression were found in both normal and renal cancer tissues, indicating that the transcriptional and translational levels of UBE2C expression in PRCC were not differential." (PMID 36385010, 2022). "We used the siRNA technique to downregulate CDC20 and UBE2C in two renal cancer cell lines to investigate their role in renal carcinoma." (PMID 36385010, 2022).
skin cancer (4 papers, 2016 to 2025). "Further bolstering the role of Cdc20 as a potential oncogene are observations in mouse skin cancer models, where inducible depletion of Cdc20 led to regression of tumors due to cell cycle arrest followed by apoptosis." (PMID 31382469, 2019). "In a tamoxifen inducible conditional Cdc20 knockout mouse (Cdc20−/lox/RERT+/Cre) chemical induced skin cancer model, ablation of Cdc20 results in Cdc20 ablation can subsequently result in complete tumor regression in vivo via apoptosis." (PMID 27418942, 2016). "Further histological analysis revealed that depletion of Cdc20 in skin tumors resulted in tumor cell arrest in metaphase, accompanied by induction of cellular apoptosis." (PMID 27418942, 2016). "Importantly, the ablation of Cdc20 in a mouse model resulted in the efficient regression of skin tumours in vivo, confirming the rationale for considering Cdc20 to be an oncoprotein." (PMID 36499653, 2022).
urothelial bladder cancer (4 papers, 2021 to 2024). "We also explore the predictive value of these six cell cycle related genes and found that CCNB1, CDC20 and CDC25C could also predict the overall survival rate of bladder urothelial carcinoma patients." (PMID 33980246, 2021).
Cirrhosis (3 papers, 2018 to 2021). A chronic disorder of the liver in which liver tissue becomes scarred and is partially replaced by regenerative nodules and fibrotic tissue resulting in loss of liver function. "CDC20 and TOP2A are two hub genes that were implicated in the pathological development from cirrhosis to HCC." (PMID 34568357, 2021).
mantle cell lymphoma (3 papers, 2022 to 2024). Mantle cell lymphoma is a rare form of malignant non-Hodgkin lymphoma affecting B lymphocytes in the lymph nodes in a region called the ``mantle zone''. "In patients with mantle cell lymphoma, high CDC20 expression correlated with unfavorable clinicopathological features and poor prognosis." (PMID 39902297, 2024). "Recent studies showed that CDC20 is highly expressed not only in DLBCL but also in mantle cell lymphoma (MCL)." (PMID 35490245, 2022).
pituitary tumor (3 papers, 2015 to 2023). A benign or malignant neoplasm affecting the pituitary gland. "Diurnal rhythm of PER2 parallels those of cell cycle genes (Ccnb2, Cdc20 and Espl1) in pituitary tumors, supporting PER2 as a driver of rhythmicity in these cell cycle genes and implicating a diurnal rhythm in cell cycle." (PMID 37215573, 2023).
sarcoma (3 papers, 2019 to 2021). A usually aggressive malignant neoplasm of the soft tissue or bone. "Amongst the eight remaining hub genes, CDC20, CCNB2, AURKB, MAD2L1, CENPE, KIF2C, and PCNA were highly expressed and related with negative prognosis of sarcoma." (PMID 31870357, 2019).
viral infections (3 papers, 2018 to 2023). "Other members of the network also reappeared in the gene set enrichment analysis as members of pathways associated with viral infections (DDX58, IFIT1, IRF1, MX1, STAT1) or viral carcinogenesis and cell cycle (CCND1, CCND3, CCNE1, CDC20, E2F2, RANBP1)." (PMID 30042828, 2018).
adrenocortical cancer (2 papers, 2017 to 2025). "•CDC20 overexpression in pediatric/adult adrenocortical carcinomas links to worse prognosis." (PMID 40688701, 2025).
diabetes (2 papers, 2022 to 2024). "Nonetheless, none of the expression of ASPM, CDC20, DLGAP5, BUB1B, CDCA8, and NCAPG was related to BMI and diabetes." (PMID 36186000, 2022).
Ewing sarcoma (2 papers, 2017 to 2018). A small round cell tumor that lacks morphologic, immunohistochemical, and electron microscopic evidence of neuroectodermal differentiation. "Whether the over-expression of CDC20 is playing a pivotal role in Ewing sarcoma cancer progression and if CDC20 is contributing to the cancer stem cell property of the Ewing sarcoma cells is an open question." (PMID 30563222, 2018). "CDC20, besides other oncogenes and tumors suppressor genes, may play an oncogenic role in the development and progression of Ewing sarcoma of at least the given type." (PMID 30563222, 2018). "Although CDC20 is seen to be over-expressed in several cancers, the role of its over-expression has not yet been discussed in Ewing sarcoma." (PMID 30563222, 2018).
female infertility (2 papers, 2021 to 2022). Diminished or absent ability of a female to achieve conception. "In female infertility, five types of mutations in CDC20 were reported to be associated with oocyte maturation arrest in female patients." (PMID 35833143, 2022). "Our study also expands the mutational spectrum of CDC20 and provides genetic diagnostic marker for female infertility." (PMID 33898437, 2021). "In conclusion, we identified three novel biallelic mutations in CDC20 that are responsible for female infertility, and this supports our previous study of CDC20 mutants." (PMID 33898437, 2021). "In that study, we identified several mutations that impaired the normal function of CDC20, which resulted in female infertility due to abnormal oocyte maturation, fertilization, or early embryonic development." (PMID 33898437, 2021). "Until 2020, the explicit causal relationship between CDC20 mutations and female infertility was established by our group." (PMID 33898437, 2021). "This study confirms our previous research and expands the spectrum of known mutations in CDC20, providing new evidence supporting the function of CDC20 in the genetic etiology of female infertility characterized by oocyte maturation arrest and fertilization failure." (PMID 33898437, 2021).
Lung Squamous Cell Carcinoma (2 papers, 2021 to 2022). "High-expressed CDC20 was related to the worst prognosis in lung squamous cell carcinoma." (PMID 35625619, 2022).
malaria (2 papers, 2012 to 2020). Malaria is a serious and sometimes fatal disease caused by a parasite that commonly infects a certain type of mosquito which feeds on humans. "Little information is available regarding CDC20 expression and localisation in the malaria parasite in both vertebrate and mosquito hosts." (PMID 22383885, 2012). "We studied the function of the single homologue of CDC20/CDH1 expressed in the rodent malaria parasite, Plasmodium berghei." (PMID 22383885, 2012). "We have also shown that CDC20 and MAP2 may play independent but essential roles in the mitotic division associated with microgametogenesis but are not essential for mitosis during asexual stages in the malaria parasite." (PMID 22383885, 2012).
nasopharyngeal carcinoma (2 papers, 2019 to 2020). A carcinoma arising from the nasopharyngeal epithelium. "CDC20 is a component of the mammalian cell-cycle mechanism and activates the anaphase-promoting complex (APC); its inhibition may enhance radio sensitivity in nasopharyngeal carcinoma cells." (PMID 30808328, 2019).
ovarian tumors (2 papers, 2019 to 2024). "Except for ATAD2, expression of other genes (ASF1B, CCNE1, CDC20, CDCA8, RECQL4, RNASEH2A, and SMC4) was upregulated in ovarian tumors compared to non-cancerous tissue." (PMID 39199556, 2024).
premature aging syndrome (2 papers, 2020 to 2022). Changes in the organism associated with senescence, occurring at an accelerated rate. "In support of this conclusion, a germline missense mutation of c.856C>A (p.R286S) in Cdc20 was found in a patient with premature aging syndrome showing random chromosome number instabilities." (PMID 35988650, 2022). "If systemic premature aging was also solely induced by the CDC20 mutation, the disease is considered a novel premature aging syndrome distinct from known MVA syndromes and premature aging syndromes." (PMID 33094908, 2020).
salivary duct carcinoma (2 papers, 2020 to 2022). An aggressive, high grade adenocarcinoma that arises from the salivary glands. "It has also been demonstrated that MAD2L1 binds with CDC20 and BUB1B and contributes to the abnormal growth of salivary duct carcinoma, despite its participation in signaling transductions." (PMID 36497125, 2022). "Despite the barely known signaling pathways it participated in, MAD2L1 is shown to interact with CDC20 and BUB1B, and correlate with aberrant development of salivary duct carcinoma." (PMID 32795325, 2020).
acral melanomas (1 paper, 2023). "The singular acral melanoma with a CDC20 promoter hotspot mutation contained the G529A variant." (PMID 38030698, 2023). "The CDC20 promoter is mutated in 39 of 183 donors in the ICGC dataset, 38 of which are skin cutaneous melanomas (27.9% of cutaneous melanomas) and one acral melanoma sample (2.9% of acral melanomas)." (PMID 38030698, 2023).
acute leukemia (1 paper, 2023). A clonal (malignant) hematopoietic disorder with an acute onset, affecting the bone marrow and the peripheral blood. "Moreover, Cell division cycle 20 homologue (CDC20), which is involved in mitotic progression, is frequently over-expressed in acute leukemias, as well as in other blood and solid tumors." (PMID 36770891, 2023).
acute liver failure (1 paper, 2023). Rapid deterioration of liver function causing encephalopathy and coagulopathy. "However, whether CDC20 works in acute liver failure remains unclear." (PMID 36911196, 2023).
adrenal carcinoma (1 paper, 2021). A carcinoma involving a adrenal gland. "In adrenal carcinoma, the CDC20 expression was significantly associated with the poor OS and PFS, the HR of both OS and PFS were the highest among all cancer types in TCGA." (PMID 34527589, 2021). "Our results presented here indicated that CDC20 also plays a critical role in the progression of adrenal carcinoma." (PMID 34527589, 2021). "The expression of CDC20 was significantly and positively correlated with the increase of clinical stages in adrenal carcinoma." (PMID 34527589, 2021). "In addition to adrenal carcinoma, it remains elusive how Cdc20 executes its oncogenic function in specific cancer." (PMID 34527589, 2021). "It is plausible that Cdc20 plays a central role and might be one of the driver factors in the tumorigenesis of adrenal carcinoma." (PMID 34527589, 2021).
adrenocortical adenoma (1 paper, 2025). "The findings revealed pronounced CDC20 expression, primarily in the cytoplasm of ACC cells, whereas adrenocortical adenoma tissues exhibited weak expression or were completely negative for CDC20." (PMID 40688701, 2025). "In order to validate the hypothesis of increased CDC20 expression in ACC tissues over non-cancerous adrenal tissues, we applied IHC staining to evaluate both the expression level and subcellular localization of CDC20 in 6 cases of ACC and 5 cases of adrenocortical adenoma." (PMID 40688701, 2025).
Alzheimer disease (1 paper, 2020). A progressive, neurodegenerative disease characterized by loss of function and death of nerve cells in several areas of the brain leading to loss of cognitive function such as memory and language. "In Alzheimer’s disease and stroke pathogenesis, APC/CCdh1 but not Cdc20, is expressed in post-mitotic mammalian neurons and the inactivation of Cdh1 by phosphorylation results in the accumulation of cyclin B1." (PMID 33218190, 2020).
asthma (1 paper, 2015). "Studies with a CDC20 inhibitor may reveal more information on its role in RAO/asthma." (PMID 26292153, 2015). "However, the role of CDC20 in regards to macrophage homeostasis and RAO/asthma needs further investigation." (PMID 26292153, 2015). "Interestingly, CDC20 has not yet been considered as a putative therapeutic target in asthma." (PMID 26292153, 2015).
Azoospermia (1 paper, 2017). Absence of any measurable level of sperm,whereby spermatozoa cannot be observed even after centrifugation of the semen pellet. "Despite these limitations, our results suggest that a CDC20 R383C mutation may result in idiopathic azoospermia." (PMID 29245942, 2017). "To investigate relative gene expression in human idiopathic non-obstructive azoospermia, we sequenced all the exons of cell division cycle 20 (CDC20) in 766 patients diagnosed with IA, as well as in 521 normally fertile men." (PMID 29245942, 2017).
B-cell NHLs (1 paper, 2019). "Together, our data indicate that Cdc20 is involved in DLBCL and MCL pathogenesis, thus supporting the preclinical testing of APC/C targeting in these aggressive B-cell NHLs." (PMID 31089208, 2019).
brain tumors (1 paper, 2016). "Moreover, using an orthotopic xenograft model overexpression of Cdc20 enhanced the GSCs to generate brain tumors, whereas depletion of Cdc20 retarded the GSCs to develop brain tumors." (PMID 27626499, 2016).
celiac disease (1 paper, 2024). An autoimmune genetic disorder with an unknown pattern of inheritance that primarily affects the digestive tract. "One gene of interest in the study of both celiac disease and OA is CDC20." (PMID 39301493, 2024). "In celiac disease, CDC20 might influence the regulation of intestinal epithelial cell proliferation, which is often disrupted in this condition." (PMID 39301493, 2024).
chordoma (1 paper, 2025). Chordomas are rare malignant tumors arising from embryonic remnants of the notochord in axial skeleton. "The ALK/MET inhibitor crizotinib, as a potential therapeutic agent for chordomas, led to a reduction of proliferation markers and the modulation of key DNA repair and cell cycle regulatory genes, with CDC20 and FOXO4 playing a pivotal role." (PMID 41442054, 2025). "The ALK/MET inhibitor crizotinib, considered a potential treatment for chordomas, reduced proliferation markers and modulated important genes related to DNA repair and cell cycle regulation, with CDC20 and FOXO4 being particularly significant." (PMID 41442054, 2025).
chronic pancreatitis (1 paper, 2012). A chronic inflammatory process causing damage and fibrosis of the pancreatic parenchyma. "Using a cDNA microarray analysis, we noted a 5-fold higher CDC20 expression in PDAC tissue when compared to expression levels in normal pancreas or chronic pancreatitis tissue (unpublished results)." (PMID 22475564, 2012). "A microarray analysis revealed 5-fold higher CDC20 expression in PDAC tissue than in chronic pancreatitis tissue." (PMID 22475564, 2012). "CDC20 was identified using a cDNA microarray database containing gene expression profiles for PDAC tissues and cell lines and chronic pancreatitis and normal pancreas tissues." (PMID 22475564, 2012).
Cognitive impairment (1 paper, 2024). Abnormal cognition is characterized by deficits in thinking, reasoning, or remembering. "BBCT significantly improved cognitive impairment in a BCAS mouse model by inhibiting microglial and astrocyte activation and regulating the expression of CDC20, EGF, TRAF1, and key proteins in the neuroactive ligand-receptor interaction and neuropeptide signaling pathways." (PMID 38464836, 2024).
ependymoma (1 paper, 2022). A WHO grade II, slow growing tumor of children and young adults, usually located intraventricularly. "PROTAC may also be a promising therapeutic strategy to target ependymoma with elevated expression of CDC20, including the ST_EPN_RELA and PF_EPN_A subgroups." (PMID 36293188, 2022).
epithelial transitional cell carcinoma (1 paper, 2021). "Compared to Urosta cells, CDC20 showed high expression (138.35 fold) in J82 cell line, a representative of epithelial transitional cell carcinoma line, and lower expression (3.98 and 8.47 fold) in HT1197 carcinoma cells and 253JB-V cells, which are metastatic variant at p-value 0.000." (PMID 34885040, 2021). "Irrespective of the tumor type, CDC20 and CTSV showed higher expression in transitional cell carcinoma." (PMID 34885040, 2021).
head and neck squamous cell carcinoma (1 paper, 2014). A squamous cell carcinoma that arises from any of the following anatomic sites: lip and oral cavity, nasal cavity, paranasal sinuses, pharynx, larynx, and salivary glands. "Overexpression of Cdc20, at mRNA levels, was reported in both OSCC-derived cell lines and primary head and neck squamous cell carcinoma (HNSCC) tissues." (PMID 24995269, 2014).
heart failure (1 paper, 2025). Inability of the heart to pump blood at an adequate rate to meet tissue metabolic requirements. "In this study, we used the tail vein method of AAV9-cTNT-CDC20 to prove that overexpression of CDC20 can inhibit DOX-induced myocardial injury in mice, thereby reducing the development of heart failure in mice, and without affecting the antitumor effect of DOX." (PMID 40045239, 2025).
hepatoblastoma (1 paper, 2026). Hepatoblastoma (HB) is a malignant hepatic tumor and is the most common pediatric liver cancer. "In hepatoblastoma, CCNA2, CDK1, and CDC20 were identified as potential therapeutic targets, with their knockdown inhibiting aggressive cell behaviors." (PMID 41511815, 2026).
ischemic stroke (1 paper, 2022). A stroke disorder caused by obstruction of blood flow to the brain, due to thrombotic (local blood clot formation) or embolic (due to a blood clot or other material traveling from another site) event. "Cdk1,Ccnb,and Cdc20, the members of module-A networks with the highest degrees, possess the potential of being biomarkers of ischemic stroke due to their function in the cell cycle." (PMID 35485294, 2022).
kidney tumor (1 paper, 2022). "Moreover, we also performed the verification of CDC20 in kidney tumor tissues in the GSE15641 dataset and obtained the same results as the former (P < 0.05)." (PMID 35800227, 2022).